IGFBP3 (insulin like growth factor binding protein 3)
Diseases named in the same sentence as IGFBP3 in open-access papers (continued):
Sharing a sentence is not in itself a finding about the gene and the disease.
breast carcinoma (continued). "The aim of the present nested case-control study was to examine associations between pre- and postoperative circulating IGF-I, IGFBP-3 and IGFBP-7 levels, and risk of breast cancer recurrence." (PMID 33767994, 2021). "High expression of IGFBP-3 is found in aggressive breast cancer, and IGFBP-3 has been shown to potentiate epidermal growth factor receptor signaling in triple negative breast cancer." (PMID 33767994, 2021). "In breast cancers, IGFBP-3 has the capability to promote tumour growth through either IGF-1-dependent or IGF-1-independent pathways 12,15." (PMID 34512163, 2021). "The risk of breast cancer recurrence was evaluated in relation to preoperative low (T1), moderate (T2), or high (T3) tertile IGF-I, IGFBP-3, IGFBP-7 levels, or IGF-I/IGFBP-3 molar ratios between cases and matched controls." (PMID 33767994, 2021). "In tumors, high IGFBP-3 levels in breast cancer tissue are correlated with rapid growth and poor prognosis." (PMID 34228231, 2021). "Insulin-like growth factor-I (IGF-I) and its binding proteins (BPs) have been associated with breast cancer risk, especially high IGF-I concentrations and the biologically active fraction estimated as the IGF-I/IGFBP-3 molar ratio." (PMID 33767994, 2021). "The prognostic role of postoperative changes in IGF-I, IGFBP-3, IGFBP-7, or IGF-I/IGFBP-3 levels in relation to breast cancer recurrence was assessed." (PMID 33767994, 2021). "First, aberrant promoter methylation of IGFBP‐3 gene, which silences its expression, is detected in human gastric cancer, colorectal cancer, breast cancer, and malignant mesothelioma cancer." (PMID 34485840, 2021). "We report a direct correlation between the expression of GRP78 and IGFBP-3 in breast cancer cell lines and tumour sections." (PMID 33352865, 2020). "Given a wealth of clinical and experimental evidence implicating a role for IGFBP-3 in the progression of breast cancer, IGFBP-3 represents a promising target for developing therapeutics for the clinical management of the disease." (PMID 33352865, 2020). "The ratio between IGF1 and circulating IGFBP3 was suggested as a potential prognostic marker in breast cancer." (PMID 32414222, 2020). "Collectively, these results highlight a role of GRP78 and IGFBP-3 in determining the outcome for breast cancer patients." (PMID 33352865, 2020). "The association of transglutaminase, which possess intrinsic tyrosine kinase activity has been demonstrated to lead to phosphorylation of IGFBP-3 in breast cancer cells." (PMID 32478064, 2020). "Evidence has shown that exogenous IGFBP3 significantly inhibits cell growth of human breast cancer cells through its specific binding to cell surface proteins." (PMID 32414222, 2020). "Our analysis of basal levels of GRP78 and IGFBP-3 in different breast cancer cell lines revealed a similar pattern of abundance, with higher levels of both proteins in the more aggressive breast cancer cells compared with the less invasive cell lines." (PMID 33352865, 2020). "We investigated the clinical significance of a recently identified association between insulin-like growth factor binding protein 3 (IGFBP-3), that plays a key role in breast cancer progression, and glucose-regulated protein 78 (GRP78)." (PMID 33352865, 2020). "IGFBP-3 induces apoptosis in Hs578T breast cancer cells by inhibiting PKA upon binding with caveolin through the caveolin scaffolding domain." (PMID 32478064, 2020). "Increased breast cancer risk was also associated with IGFBP-3 elevation in this pooled analysis (p trend = 0.062), with an OR of 1.13 (0.99–1.28) at the highest IGFBP-3 quintile." (PMID 33092613, 2020).
breast carcinoma (continued). "We next evaluated the clinical relevance of our in vitro observations by examining the status of GRP78 and IGFBP-3 in tumour sections and how this related to breast cancer prognosis." (PMID 33352865, 2020). "Generally, our findings are consistent with previous studies, demonstrating the role of exogenous IGFBP3 as a mediator doxorubicin-induced senescence of breast cancer cells, as well as replicative senescence of umbilical vein endothelial cells." (PMID 31951594, 2020). "As a matter of fact, in breast cancer there are reports indicating high expression of IGFBP-3 with poor prognosis and survival outcome." (PMID 32478064, 2020). "On silencing GRP78 in breast cancer cells we observed a switch in the actions of IGFBP-3 from increasing to inhibiting apoptosis and inhibiting to promoting invasion." (PMID 33352865, 2020). "In breast cancer cells, IGFBP-3 was found to promote autophagy thereby augmenting cell survival during nutrition deprivation and hypoxia." (PMID 32478064, 2020). "Here we report a direct correlation between the expression of GRP78 and IGFBP-3 in breast cancer cell lines and tumour sections." (PMID 33352865, 2020). "In breast cancer cells, IGFBP-3 interactions with PPAR-Υ has been demonstrated that results in inhibition of cell growth." (PMID 32478064, 2020). "With breast cancer cells, in vitro IGFBP-3 enhanced induced apoptosis, however when GRP78 expression was silenced the actions of IGFBP-3 were switched from increasing to inhibiting ceramide (C2)-induced cell death and promoted cell invasion." (PMID 33352865, 2020). "Accumulating researches indicated that IGFBP3 played an important role in regulating cell cycle and apoptosis in various cancers, including breast cancer, nasopharyngeal carcinoma, OS, etcetera." (PMID 33041662, 2020). "Studies have shown that both breast cancer development and recurrence are associated with IGF-1 and IGFBP-3 levels in women." (PMID 33092613, 2020). "We have shown previously that the ability of IGFBP-3 to modulate inducers of apoptosis is matrix-dependent, with exogenous IGFBP-3 promoting cell survival of breast cancer cells when they were plated on fibronectin but enhancing when exposed to collagen." (PMID 33352865, 2020). "We have shown that GRP78 is an important component in determining the effects of IGFBP-3 on cell phenotypes and in the survival of patients with breast cancer." (PMID 33352865, 2020). "In vitro tests which confirmed the efficacy of inhibiting further growth of the colon and breast cancer cells by using recombinant IGFBP-3 were also interesting." (PMID 31565100, 2019). "Dysregulation of IGFBPs as a result of epigenetic modifications has been identified in many tumours, such as aberrant DNA methylation of the promoter of IGFBP-2 and IGFBP-3 genes in hepatomas and breast cancers respectively." (PMID 31903164, 2019). "On the other hand, prior studies have denoted the importance of circulation IGF1/IGFBP-3 M ratio in almost different malignancies, such as breast cancer." (PMID 31752829, 2019). "Text mining of PubMed literature with an R package RISmed revealed that most of them are with unclear roles in breast cancer except for Igfbp3, Mmp14, Fap, Timp3 and Wnt5a." (PMID 29615825, 2018). "Knockdown of ELK-1, a member of the Ets family of transcription factors, significantly reduced hypoxic induction of the HIF-2α target genes, including CITED2, WISP2, and IGFBP3 in MCF-7 breast cancer cells." (PMID 30478339, 2018). "In contrast, CXCL10 and IGFBP-3 were shown to have anti-malignant properties by anti-angiogenic action or the inhibition of breast cancer cell proliferation." (PMID 28763032, 2017). "In general, an increased status of IGFBP3 correlates with a poor prognosis in cancer, at-large, including in breast cancer." (PMID 28393842, 2017). "We first searched for possible correlations between MTA1, DNMT3a, and IGFBP3 using eight breast cancer datasets." (PMID 28393842, 2017).
breast carcinoma (continued). "Together findings presented here recognize an inherent role of MTA1 as a modifier of DNMT3a and IGFBP3 expression, and consequently, the role of MTA1-DNMT3a-IGFBP3 axis in breast cancer progression." (PMID 28393842, 2017). "In brief, findings presented here identified an upstream regulatory role of MTA1 coregulator in controlling the expression of DNMT3a and IGFBP3 in cancer cells and possibly modifying the biology of breast cancer progression." (PMID 28393842, 2017). "Our current results suggest that long-term DHEA feeding can also protect against liver steatosis by reducing body weight gain and reducing serum IGF-1 and IGFBP-3 in an obese breast cancer model." (PMID 28335515, 2017). "Our results suggest that DHEA feeding can protect against liver steatosis by reducing body weight gain and modulating serum IGF-1 and IGFBP-3 levels in an obese breast cancer rat model." (PMID 28335515, 2017). "We examined the associations of 22 polymorphisms across five IGF1 pathway genes (IGF1, IGFBP3, IGF1R, IRS1, and PI3KCB) with risk of breast cancer among women of European and East Asian descent." (PMID 27376028, 2016). "Rice and colleagues found that higher IGF-I levels and IGF-I:IGFBP-3 ratios were associated with less involuted TDLU categories, based on visual evaluation, which in turn was related to increased risk of breast cancer among women with benign breast disease." (PMID 26893016, 2016). "All of the studies included evaluated the serum concentrations of IGFBP-3 and demonstrated that exercise training significantly increased the serum levels of this biomarker in women with breast cancer (SMD = 0.54, 95 % CI 0.27 – 0.80; I2 = 84.2 %)." (PMID 27562357, 2016). "Wild-type (WT) C57BL/6 or IGFBP-3-null (BP3KO) mice were fed a high-fat diet (HFD) or control chow-diet for 15 weeks before orthotopic injection with syngeneic EO771 murine breast cancer cells." (PMID 27448965, 2016). "The most remarkable finding from this meta-analysis was that exercise training improved the serum levels of IGF-I, IGF-II, IGFBP-I and IGFBP-3 in breast cancer survivors after successful anticancer treatment." (PMID 27562357, 2016). "We found that exercise training increased IGFBP-3 serum levels in breast cancer survivors, although high statistical heterogeneity was observed in the overall effect estimate (I2 = 84.2 %)." (PMID 27562357, 2016). "A major finding is that not only high-fat feeding, but also host-derived IGFBP-3, stimulated mammary tumor growth." (PMID 27448965, 2016). "A small cohort study in breast cancer examining serum IGFBP-3 levels before and 1 week after palliative chemotherapy demonstrated that patients who showed decreased IGFBP-3 levels after treatment showed poorer OS." (PMID 26217584, 2015). "The relationship between pre-diagnostic levels of IGF-I and IGF binding protein-3 (IGFBP-3) and breast cancer risk was examined in a meta-analysis of data from 17 prospective studies conducted in 12 countries." (PMID 26251693, 2015). "Native Hawaiians with IGFBP3-positive tumors had poorer overall and breast cancer-specific survival compared to IGFBP3-negative tumors (Log-rank P = 0.03 and Log-rank P = 0.01, respectively)." (PMID 25619494, 2015). "In contrast, Western blot analysis showed that the levels of secreted IGFBP-3 in the conditioned medium, visible as a 35-40 kDa doublet, were highest in the ER-negative breast cancer cell lines compared with the ER-positive lines." (PMID 26378048, 2015). "Hs578T breast cancer cells, which also express HRas, were similarly resistant to the inhibitory effects of IGFBP-3 but were resensitized to it in the presence of PD98059, an inhibitor of p44/42MAPK." (PMID 26221601, 2015). "This is the first study to evaluate the relationship of tissue expression of IGF1, IGFR1, IGFBP2, and IGFBP3 and survival in US breast cancer patients of Asian, Pacific Islander, and Caucasian ancestry." (PMID 25619494, 2015).
breast carcinoma (continued). "Delineating IGFBP3's prognostic role in breast cancer survival is complicated due to its ability to both promote and inhibit cellular proliferation." (PMID 25619494, 2015). "It seems counterintuitive that IGFBP-3, a protein that has been shown in numerous breast cancer cell studies to be growth inhibitory and proapoptotic, is associated with aggressive forms of breast cancer." (PMID 26221601, 2015). "Both cell culture and xenograft tumor models have shown that overexpression of IGFBP-3 can indeed result in enhanced growth of breast cancer cells." (PMID 26221601, 2015). "TGFβR binding (F9) regulates insulin-like growth factor binding protein (F5) (IGFBP)-3 production, which is a major antiproliferative factor and a key element for TGFβ-induced growth inhibition in breast cancer cells." (PMID 24997799, 2014). "These include gene silencing through aberrant hypermethylation (e.g. IGFBP3) and affect genes characterizing breast cancer sub-types (e.g. ERBB2)." (PMID 25071007, 2014). "In this study, using Hs578T human breast cancer cells, the authors have dissected a signaling cascade activated by IGFBP3, shedding new light on IGF-independent, complex effects of IGFBP3 on apoptosis." (PMID 25374561, 2014). "Identified members included those previously shown to be aberrantly silenced through DNA hypermethyaltion in UCC, e.g. IGFBP3, and those found to charactize breast cancer sub-types (e.g. ERBB2)." (PMID 25071007, 2014). "Along these lines, chromatin interacting with IGFBP3 in the breast cancer cell lines was significantly enriched for methylated promoters relative to HMEC, with MCF7 showing the greatest fold increase." (PMID 24019942, 2013). "In contrast, IGFBP-3 treatment was effective in inhibiting IGF-I/Akt pathways in both breast cancer lines." (PMID 23690781, 2013). "There is a significant increase in the proportion of methylated promoters that participated in long-range interactions with IGFBP3 in both breast cancer cell lines relative to HMEC." (PMID 24019942, 2013). "The initial reaction of ER positive T47D breast cancer cells to IGFBP3 is inhibitory, yet prolonged expression of IGFBP3 cDNA stimulates growth." (PMID 24019942, 2013). "The aim of our study was to evaluate the role of IGFBP-3 in 1, 25-D3-induced apoptosis in breast cancer cells." (PMID 23690781, 2013). "A similar pattern of IGFBP3 insensitivity was observed in Hs578T breast cancer cells that endogenously express Hras." (PMID 24039934, 2013). "Increased IGFBP3 expression has been shown to enhance survival of breast cancer cells exposed to environmental stress." (PMID 24019942, 2013). "While correlations between serum levels of IGFBP3 and breast cancer have yielded contradictory results, increased levels of IGFBP3 in breast cancer tissue is correlated with a worse prognosis and poor clinical features." (PMID 24019942, 2013). "To better understand the role of IGFBP3 in breast cancer, we analyzed its expression in primary breast cells, the estrogen receptor alpha (ERα) positive breast cancer cell line MCF7, and the triple-negative breast cancer cell line MDA-MB-231." (PMID 24019942, 2013). "In the least malignant breast cancer cell lines, IGFBP3 plays an inhibitory role as a tumor suppressor, and this function is reversed in highly malignant breast cancer cells which express higher levels of IGFBP3." (PMID 24039934, 2013). "A number of growth factors and hormones, including 1, 25-D3, have been shown to induce the expression of IGFBP-3 in breast cancer cell lines." (PMID 23690781, 2013). "We sought to explore global differences of IGFBP3 long-range interaction profiles between normal breast cells and breast cancer cell lines." (PMID 24019942, 2013). "Studies from our group, and others, have identified that the pathway directed along the Insulin-like Growth Factor (IGF) axis (specifically involving IGF-I, IGFBP3, down the PI3K/Akt cascade to FOXO1) is strongly associated with breast cancer outcomes." (PMID 24167614, 2013).
breast carcinoma (continued). "In this study, we examined IGFBP3 long-range interactions and show that the three-dimensional structure of the genome changes dramatically in breast cancer." (PMID 24019942, 2013). "This resistance or insensitivity of breast cancer cells to IGFBP3 inhibition, it turns out, is a result of oncogenic ras activation." (PMID 24039934, 2013). "Previous studies on polymorphisms/haplotypes in IGFI, IGFBP3 and IGFALS and their association to breast cancer susceptibility and circulating levels of both IGFI and IGFBP3 have been reported making them interesting targets in mammographic density studies." (PMID 20302654, 2010). "Our findings are consistent with two previous studies that comprehensively examined the role of IGF1, IGFBP1, and IGFBP3 genetic variation in relation to circulating IGF-I and IGFBP-3 levels and breast cancer risk." (PMID 18596909, 2008). "Our data suggest that, among premenopausal women, the associations of some breast cancer risk factors with intact levels of IGFBP-3 are different from those with total (intact and fragmented) IGFBP-3 levels." (PMID 18471292, 2008). "As to IGFBP-3, higher serum IGFBP-3 levels to the increased risk of premenopausal breast cancer and distant recurrence of postmenopausal and estrogen receptor-positive breast cancer were observed." (PMID 18781172, 2008). "Most previous studies have focused on evaluating the association between circulating insulin-like growth factor binding protein 3 (IGFBP-3) levels and breast cancer risk." (PMID 17210081, 2007). "IGFBP-3 has been shown to induce apoptosis of breast cancer cells and inhibit breast cell growth in IGF-independent ways." (PMID 17210081, 2007). "Few studies have compared the expression level of the IGFBP3 gene in breast cancer tissues with those in adjacent normal tissues or the expression levels across groups of patients with different diagnoses of breast diseases." (PMID 17210081, 2007). "IGFBP3 gene expression was systematically evaluated in tumor tissue and adjacent normal tissues from patients diagnosed with breast cancer or BBD." (PMID 17210081, 2007). "In contrast, studies measuring IGFBP-3 protein levels in a series of human breast cancer tissues showed higher IGFBP-3 levels in ER-negative than in ER-positive tumors." (PMID 17210081, 2007). "In contrast, in patients with breast cancer, IGFBP3 expression levels in the tumor were lower than the adjacent normal tissue, although the difference was not statistically significant." (PMID 17210081, 2007). "It has been shown that IGFBP-3 inhibits the growth of the IGF-unresponsive Hs578 human breast cancer cell line and enhances the effects of ceramide and paclitaxol-induced apoptosis directly." (PMID 17210081, 2007). "Pekonen and colleagues reported that mRNA levels of IGFBP3 and other IGFBPs were significantly higher in five breast cancer tissues than in adjacent normal tissues as measured by Western blotting." (PMID 17210081, 2007). "To understand the role of IGFBP-3 in breast tumorigenesis, we investigated IGFBP3 mRNA expression levels in benign and malignant breast tumors and their adjacent normal tissues using real-time quantitative PCR." (PMID 17210081, 2007). "We have performed a large-scale association study, nested in the EPIC cohort, to assess the role of genetic variation of IGF1 and of the genes encoding the major IGF-I binding proteins on risk of breast cancer and on circulating levels of IGF-I and IGFBP-3." (PMID 16404426, 2006). "The potential to switch the IGFBP-3 action on cell growth suggests that IGFBP-3 has a role in malignant progression of breast cancer cells with insensitivity to IGFBP-3 growth inhibition through the expression of oncogenic Ras." (PMID 15642160, 2005). "This study suggests that most breast cancers express epithelial IGFBP-3 (1+/2+), mostly with a weak/moderate immunoreactivity (1+)." (PMID 15642160, 2005).